STS (steroid sulfatase)
Diseases named in the same sentence as STS in open-access papers (continued):
Sharing a sentence is not in itself a finding about the gene and the disease.
endometriosis (11 papers, 2015 to 2025). The growth of functional endometrial tissue in anatomic sites outside the uterine body. "The gene encoding ARO, CYP19A1, was detected in all endometriosis tissue at levels all greater than found in control; STS and HSD17B1 presented consistently higher mRNA expression levels in DIE." (PMID 35591944, 2022). "One phase 2 clinical trial explored the use of an STS inhibitor in endometriosis patients (NCT01631981)." (PMID 37188267, 2023). "Increased miR-142-3p seems to reduce steroid sulfatase and IL-6 activity, suggesting a dual effect on steroidogenic and inflammatory pathways in endometriosis." (PMID 35054341, 2022). "On the other hand, the lack of difference between gene and protein expression for the ratio HSD17B1:STS, in different endometriosis sites indicates that these enzymes are more closely regulated, as they show less expression variation." (PMID 35591944, 2022). "STS inhibitors reduce STS activity in endometriotic implants, and inhibition of STS in murine models of endometriosis decreases disease severity." (PMID 26213785, 2015). "The high level of STS activity detected in ectopic endometrium and its correlation with disease severity suggest that STS inhibitors could be used to treat endometriosis." (PMID 39062484, 2024). "Notably, higher expression of steroid sulfatase (STS) was observed in stromal cells from the eutopic endometrium of patients with endometriosis." (PMID 31878927, 2019). "Indeed, SULT1E1 protein has been shown to be down-regulated in human endometriosis tissue, and increasing STS activity correlates with disease severity." (PMID 26213785, 2015). "STS inhibitor PGL 2001 (estradiol sulfamate, E2MATE) was tested in 162 patients with endometriosis with concomitant administration of progestin NETA (Norethisterone Acetate)." (PMID 37188267, 2023). "Overview of the trials registered in the database Clinical Trials (ClinicalTrails.gov) for the use of aromatase, STS and HSD17B1 inhibitors in breast, endometrial, ovarian, prostate cancers and endometriosis." (PMID 37188267, 2023). "The enzymes STS and HSD17B1 have been considered important in the pathogenesis of endometriosis, as indicated by the use of their inhibitors in the treatment of endometriosis." (PMID 35591944, 2022). "Gene expression ratio among CYP19A1, STS, and HSD17B1 in biopsies from endometriotic lesions and from eutopic endometrium of non-endometriosis patients (control)." (PMID 35591944, 2022). "The STS mRNA expression levels in patients with endometriosis were significantly higher than those in patients without endometriosis." (PMID 39062484, 2024). "Our data show that the relative expression of ARO, STS, and HSD17B1 vary in endometriotic tissue obtained from deep infiltrating lesions (DIE), superficial (SUP), ovarian (OMA), and eutopic endometrium from endometriosis patients (EE) lend support to the hypothesis." (PMID 35591944, 2022). "Data on the expression of the STS and SULT genes at the mRNA, protein and enzymatic activity levels in endometriosis tissue vs. control tissue are contradictory and do not fully support the importance of the sulfatase pathway." (PMID 26924986, 2016).
ichthyosis (10 papers, 2016 to 2025). Disorders of cornification that are characterized by visible scaling and/or hyperkeratosis of most or all of the skin. "STS‐encoding steroid sulfatase is a causative gene for X‐linked ichthyosis, which is characterized by ichthyosis from birth and cognitive behavioral features such as intellectual disability, ADHD, and ASD." (PMID 32913952, 2020). "Recessive X-linked ichthyosis (RXLI), a genetic disorder caused by deletion or point mutations of the steroid sulfatase (STS) gene, is the second most common form of ichthyosis." (PMID 37363400, 2023). "Ichthyosis vulgaris (IV; OMIM: # 146700) is the most common type of hereditary ichthyosis related to the filaggrin gene (FLG; OMIM: # 135940), followed by the X-linked recessive ichthyosis (XLI; OMIM: 308100) which is related to the steroid sulfatase gene (STS; OMIM: # 300747)." (PMID 40282340, 2025). "STS deficiency (STSD) due to deletions or inactivating mutations in the X-linked STS gene manifests with ichthyosis, but androgen synthesis and metabolism in STSD have not been studied in detail yet." (PMID 27003302, 2016). "It is therefore necessary to analyze both steroid sulfatase (STS) and filaggrin (FLG) genes to exclude combined forms of ichthyosis." (PMID 37623486, 2023).
prostate carcinoma (10 papers, 2013 to 2025). A carcinoma that arises from epithelial cells of the prostate gland. "This study investigates how steroid sulfatase modifies mitochondrial programming in treatment-resistant prostate cancer cells." (PMID 40563609, 2025). "STS expression has also been considered important for in situ androgen production as well as estrogen production in human prostate cancers." (PMID 28977889, 2017). "STS activity is also present in DU-145 and PC-3 prostate cancer cells and in human prostate cancer biopsies." (PMID 26213785, 2015). "Obviously, interest has focused on the prostate because it is known that prostate cancer cells possess STS activity to desulfate DHEAS, followed by downstream conversion of DHEA to androstenedione resulting in androgen receptor (AR) activation." (PMID 26213785, 2015). "Our study demonstrates that disrupting enhanced mitochondrial respiration, driven by steroid sulfatase, could provide a strategy for improving drug resistance in advanced prostate cancer." (PMID 40563609, 2025). "STS is involved in local production and metabolism of estrogens in human prostate cancers." (PMID 28977889, 2017). "In cancer, where the desulfation of E1 and DHEA may play important roles in breast and prostate cancer, STS inhibitors may show significant promise." (PMID 26213785, 2015). "For instance, DHEA-S is a depot for local androgen synthesis in prostate cancer patients also after hormone therapy using 17a-hydroxylase-17,20-lyase (CYP17A1) inhibitors, and STS inhibitors demonstrated useful for the treatment of prostate cancer resistant to anti-androgen drugs." (PMID 37188267, 2023). "Indeed, prostate cancer patients exhibit significantly elevated circulating DHT and DHTS concentrations compared to aged-matched controls, suggesting their importance in this malignancy's development and a potential further role for STS in active androgen formation." (PMID 26213785, 2015).
steroid sulfatase deficiency (9 papers, 2012 to 2025). "X-linked recessive ichthyosis (XLI) is caused by mutations in the steroid sulfatase (STS) gene and is usually present soon after birth." (PMID 35840979, 2022).
breast tumors (7 papers, 2005 to 2022). "In contrast to aromatase, STS activity is present in most cancer cases (e.g. STS expression is detected in 90% of breast tumours)." (PMID 32363947, 2020). "This may provide a genotype-dependent reservoir of inactivated metabolite, which can be desulfated by steroid sulfatase expressed in breast tumours and can be recovered to the active 4-OH-tamoxifen, leading to a prolonged anti-oestrogen effect." (PMID 15987423, 2005).
ovarian carcinoma (7 papers, 2013 to 2024). A malignant neoplasm originating from the surface ovarian epithelium. "17beta-DSH type 1 and 5 and STS were previously detected in samples from ovarian cancer patients at the mRNA and protein levels." (PMID 23476785, 2013). "However, the importance of sulfated steroids and steroid sulfatase has been less explored in ovarian cancer and thus the involvement of the enzyme on patient survival remains controversial." (PMID 34321053, 2021). "In addition to STS activity, other enzymatic activities that are also necessary for local formation of androgens and estrogen have been observed in tissue samples of ovarian cancer, including conversion of DHEA to androstenedione, and conversions between E2, E1, testosterone, and androstenedione." (PMID 28674494, 2017). "This mini-review aims to present the current state of knowledge on the role of sulfatase (STS) and sulfotransferases (SULT) in gynecological cancers, endometrial cancer (EC) and ovarian cancer (OC)." (PMID 38994718, 2024). "Steroid sulfatase (STS), estrogen sulfotransferase (EST), and 17b-hydroxysteroid dehydrogenases 2 (17BHSD2) and 5 (17BHSD5) have been detected in ovarian cancer cell lines, with a higher formation of estradiol in comparison to normal ovarian epithelium cells." (PMID 30386380, 2018). "High STS activity was detected in epithelial ovarian cancer tissue, and also in the SKOV-3 and PEO-1 ovarian cancer cell lines." (PMID 28674494, 2017). "The importance of the local formation of E2 via the sulfatase pathway is supported by high levels of STS and significantly down-regulated SULT1E1 together with metabolism of E1-S to E1 and E2 in tissue samples and model cell lines of ovarian cancer." (PMID 28674494, 2017). "Also studies in our lab show high levels of STS and moderate to low expression of SULT1E1 in a collective of patients with advanced ovarian cancer." (PMID 23476785, 2013). "Therefore, as a consequence of inhibition of STS, the low expression levels of CYP19A1 in endometrial and ovarian cancers might be up-regulated as well." (PMID 28674494, 2017).
endometrial cancer (6 papers, 2015 to 2024). Primary or metastatic malignant neoplasm involving the endometrium (mucous membrane that lines the endometrial cavity). "Increased STS activity and expression are also associated with endometrial cancer." (PMID 26213785, 2015). "The crucial role of sulfatase was also confirmed in mouse endometrial cancer xenograft model where STS inhibitor STX64 significantly inhibited tumour growth." (PMID 34805270, 2021). "Irosustat (STX64) is a potent tricylic coumarin-based sulfamate that irreversibly blocks STS activity, and it has been examined in phase II clinical trials for the treatment of patients with advanced hormone-dependent breast and endometrial cancers." (PMID 28674494, 2017). "Although the expression of the STS and SULT1E1 genes in diseased vs. control endometrium has differed between studies, all of the published data show higher mRNA and protein levels for STS than SULT1E1 in endometrial cancer tissue vs. control endometrium." (PMID 26924986, 2016). "Increased DHEA-S STS activity has also been observed in endometrial cancer, compared to normal endometrium." (PMID 26924986, 2016). "At the cellular level, STS immunoreactivity in endometrial cancer tissue was higher compared to normal endometrium, which suggests increased availability of the biologically active estrogens." (PMID 26924986, 2016). "In line with this, immunohistochemical data and early metabolism studies have shown significantly higher E1-S STS activity in endometrial cancer tissue, compared to control endometrium." (PMID 26924986, 2016). "The majority of the published data also shows increased E1-S STS activity in endometrial cancer, and thus supports E2 formation via the STS pathway." (PMID 26924986, 2016). "In endometrial cancer, studies that compared cancer tissue with adjacent morphologically normal tissue reported unchanged or increased STS expression." (PMID 37188267, 2023). "Thus, in patients with advanced and recurrent disease, irosustat showed much lower clinical benefit compared to progestin megestrol acetate, which questioned the suitability of STS inhibitors for treatment of endometrial cancer." (PMID 26924986, 2016). "Expression of STS and its activity in endometrial cancer have been evaluated in nine studies." (PMID 26924986, 2016). "Thus, attenuating both estrogenic and androgenic sex steroids through STS inhibition appears to be a feasible therapeutic strategy in endometrial cancer." (PMID 26213785, 2015). "However, future studies will examine the effects of combining STS inhibition with standard treatment options for endometrial cancer patients." (PMID 26213785, 2015). "However, STS protein levels did not associate with progression free or overall survival in 59 patients with endometrial cancer." (PMID 37188267, 2023). "STS inhibitor STX64, also known as irosustat, has also been investigated in a phase II clinical study (NCT00910091) in patients with advanced/metastatic or recurrent endometrial cancer." (PMID 34805270, 2021). "Unfortunately, phase II trials of Irosustat as a monotherapy in endometrial cancer patients were discontinued in 2011 after data indicated no beneficial effect of STS inhibition when compared to megestrol acetate." (PMID 26213785, 2015). "Although aromatase activity is not present in endometrial tissue, STS activity is increased up to 12-fold in human endometrial cancer tissue." (PMID 26213785, 2015).
attention deficit-hyperactivity disorder (4 papers, 2010 to 2017). A disorder characterized by a marked pattern of inattention and/or hyperactivity-impulsivity that is inconsistent with developmental level and clearly interferes with functioning in at least two settings (e.g. at home and at school). "Cytogenetic deletions on the short arm of the X chromosome encompassing the steroid sulfatase (STS) gene have been noted in cases of neurodevelopmental disorders associated with abnormal cognition, including attention deficit hyperactivity disorder (ADHD), schizophrenia and autism." (PMID 21255266, 2011). "This study examined the relationships among polymorphisms of the STS gene and SULT2A1 gene, dehydroepiandrosterone (DHEA) and its sulfated form (DHEA-S), and characteristics of attention-deficit/hyperactivity disorder (ADHD)." (PMID 28367959, 2017).
autism (4 papers, 2011 to 2018). Persistent deficits in social interaction and communication and interaction as well as a markedly restricted repertoire of activity and interest as well as repetitive patterns of behavior. "The 39,XY*O mouse, which lacks the orthologues of the ADHD and autism candidate genes STS (steroid sulphatase) and ASMT (acetylserotonin O-methyltransferase), exhibits behavioural phenotypes relevant to developmental disorders." (PMID 24602487, 2014). "Moreover, emerging evidence from animal models and clinical observations also suggest a role for targeting X-linked (e.g., steroid sulfatase) or-Y-linked (SRY, neuroligin-4) genes for male-biased neurodevelopmental disorders such as autism or ADHD." (PMID 30104506, 2018).
psychosis (4 papers, 2017 to 2021). "We previously proposed that STS deficiency may predispose to postpartum psychosis." (PMID 30768640, 2019). "Hence, we have previously hypothesised that deficiency for the STS enzyme might result in an increased risk of postpartum psychopathology, notably for postpartum psychosis-related phenotypes." (PMID 30768640, 2019). "A study of two female cases with STS deficiency has suggested a possible link to psychotic disorder (paranoid schizophrenia), although traits related to psychosis were not enriched in larger samples of STS-deficient women." (PMID 33219387, 2021).
Anxiety (3 papers, 2012 to 2021). Intense feelings of nervousness, tension, or panic often arise in response to interpersonal stresses. "The effects of steroid sulfatase deficiency on homecage activity, feeding/drinking behaviours, anxiety-related behaviours (assayed in light-dark box and open field paradigms), social dominance and serum steroid hormone levels were determined by comparing 40,XY and 39,XY*O mice." (PMID 21723668, 2012). "Overall, our results indicate that steroid sulfatase may have temporally dissociable effects on the distinct brain substrates underlying attention and activity/anxiety." (PMID 21723668, 2012). "The pharmacological study indicated that acute inhibition of the steroid sulfatase enzyme did not recapitulate the effects of Sts gene deficiency on activity and anxiety-related behaviour." (PMID 21723668, 2012).
cardiac arrhythmia (3 papers, 2020 to 2024). Any disturbances of the normal rhythmic beating of the heart or MYOCARDIAL CONTRACTION. "Given that the STS gene (and associated enzyme) is expressed more highly in female than male tissues as a consequence of its escape from X-inactivation, these studies might also shed light upon the sex-biased nature of cardiac arrhythmia risk." (PMID 38571328, 2024).
mood disorder (3 papers, 2019 to 2021). A cognitive disorder a disturbance in which the person's mood is hypothesized to be the main underlying feature. "We describe new findings relating to the role of the enzyme steroid sulfatase in maternal postpartum behavioural processes, and discuss how these point to a novel molecular risk pathway underlying postpartum mood disorders." (PMID 33219387, 2021). "Below, we argue that the enzyme steroid sulfatase may be a mediator of maternal behaviour, and that the downstream pathways it influences may be disrupted in idiopathic postpartum mood disorders." (PMID 33219387, 2021).
cervical carcinoma (2 papers, 2017 to 2022). A carcinoma arising from either the exocervical squamous epithelium or the endocervical glandular epithelium. "In HeLa cervical carcinoma cells, it was found that steroid sulfatase (STS), which, in addition to estrone sulfate (E1-S), also converts other steroid sulfates such as DHEA-S to DHEA (dehydroepiandrosterone, prasterone), drives the Warburg effect." (PMID 35563441, 2022).
Intellectual disability (2 papers, 2020). "Patient 2 of Esplin and three CNV patients from Decipher (DCP280938, DCP250671, and DCP251340) involving HDHD1, STS, VCX, PNPLA4 also display intellectual disability." (PMID 31963867, 2020).
Turner syndrome (2 papers, 2022). Turner syndrome is a chromosomal disorder associated with the complete or partial absence of an X chromosome. "Contiguous gene deletion syndrome at Xp22.3 resulting in nullisomy in males or Turner syndrome patients typically encompasses the steroid sulfatase gene (STS) and contiguously located other genes expanding the phenotype." (PMID 35115028, 2022). "Of the escape genes, SHOX, STS, KDM5C, KDM6A, UBA1, and RPS4X were associated with Turner syndrome." (PMID 36457060, 2022).
type 2 diabetes (2 papers, 2014 to 2020). "In genetic (ob/ob) or environmental (high-fat diet-induced) models of obesity or of type 2 diabetes steroid sulfatase was induced in the liver." (PMID 25400333, 2014). "In mouse models, both steroid sulfatase and oestrogen sulfotransferase (EST) have been demonstrated to interfere with the pathogenesis of type 2 diabetes in a sex-specific manner." (PMID 31754750, 2020).
age (1 paper, 2024). A temporal measurement of the time period elapsed since an identifiable point in the life cycle of an organism. "Steroid sulphatase (STS) cleaves sulphate groups from steroid hormones, and steroid (sulphate) levels correlate with mood and age‐related cognitive decline." (PMID 38704684, 2024).
Anosmia (1 paper, 2016). An inability to perceive odors. "This is important given the fact that XLI has been associated with anosmia and corneal opacities in some cases, and that steroid sulfatase is expressed in the developing tongue." (PMID 27711218, 2016).
atrial fibrillation (1 paper, 2024). A disorder characterized by an electrocardiographic finding of a supraventricular arrhythmia characterized by the replacement of consistent P waves by rapid oscillations or fibrillatory waves that vary in size, shape and timing and are accompanied by an irregular ventricular response. "Recently it was reported that male STS deletion carriers show an increased incidence of sinus bradycardia, atrial fibrillation (AF) and atrial flutter (10.5% versus 2.7% in male controls), possibly by affecting circulating dehydroepiandrosterone sulfate levels." (PMID 39150468, 2024).